LINC01783 (long independently transcribed non-coding RNA 1783)
Gene: Long non-coding RNA gene on chromosome 1 (16,514,977 to 16,535,707, reverse strand). Ensembl gene ENSG00000233421.
Gene Ontology:
Molecular function: triplet codon-amino acid adaptor activity
Biological process: translation
Diseases named in the same sentence as LINC01783 in open-access papers:
LINC01783 is named in the same sentence as 4 diseases in open-access papers, as found by Europe PMC text mining. Sharing a sentence is not in itself a finding about the gene and the disease. The quoted sentences say what the papers report.
cervical cancer (2 papers, 2021). A primary or metastatic malignant neoplasm involving the cervix. "Recently, a study noted that a novel lncRNA LINC01783 has been revealed to be up‐regulated in cervical cancer and LINC01783 overexpression enhanced cervical cancer cell migration, invasion and growth and inhibited cell apoptosis." (PMID 34363308, 2021). "Recently, a study illustrated that a novel lncRNA LINC01783 has been revealed to be overexpressed in cervical cancer and LINC01783 overexpression enhanced cervical cancer cell migration, invasion and growth and inhibited cell apoptosis." (PMID 34363308, 2021). "LINC01783 has been identified as an oncogene in the process of cervical cancer through targeting miR-199b-5p/GBP1." (PMID 33902591, 2021).
cancer (1 paper, 2020). A tumor composed of atypical neoplastic, often pleomorphic cells that invade other tissues. "Among lncRNAs in the ceRNA, LINC01504, LINC01783, and THUMPD3-AS1 were related to prognosis, indicating their important role in the development of cancer." (PMID 33633568, 2020).
LINC01783 also shares sentences with these, for which no sentence is quoted: tongue squamous cell carcinoma (1 paper); tumour (1).